TRPM2 (transient receptor potential cation channel subfamily M member 2)
Diseases named in the same sentence as TRPM2 in open-access papers (continued):
Sharing a sentence is not in itself a finding about the gene and the disease.
prostate carcinoma (21 papers, 2015 to 2026). A carcinoma that arises from epithelial cells of the prostate gland. "TRPM2, ITGB2, and ETS2 are located on chromosome 21 and are associated with breast, ovarian, and prostate cancers." (PMID 38803515, 2024). "These outcomes recommend that the reduced TRPM2 can be a therapeutic way to regulate prostate cancer development." (PMID 37337283, 2023). "Conversely, TRPM2-expression was downregulated in prostate cancer and in the brain and central nervous system cancers." (PMID 36046118, 2021). "The TRPM2 channel has been shown to play a role in prostate cancer particularly in prostate cancer cell proliferation." (PMID 29875336, 2018). "As these results are consistent with the nuclear TRPM2 localization in prostate cancer cells shown previously, our data thus demonstrate that TRPM2 is present in the nuclei of MCF-7 and MDA-MB-231 human breast adenocarcinoma cells." (PMID 25760245, 2015). "In this same study, it was shown that TRPM2, normally localized to the plasma membrane or lysosomal membrane, was localized to the nucleus in prostate cancer cells." (PMID 25760245, 2015). "Inhibition or RNAi silencing of TRPM2 in prostate cancer cells led to decreased proliferation, while equivalent treatments failed to decrease proliferation in noncancerous prostate cells." (PMID 26178079, 2015). "TRPM2 plays important role in the proliferation of prostate cancer cells." (PMID 37337283, 2023). "TRPM2 has been proved to promote the growth of prostate cancer cells." (PMID 35813831, 2022). "TRPM2 (and its long noncoding RNA TRPM2-AS) is also overexpressed in prostate cancer." (PMID 32887395, 2020). "Indeed, the levels of TRPM2 mRNA are higher in prostate cancer tissue and in LnCaP and PC3 cell lines." (PMID 29875336, 2018). "Completing the present picture of a broad and mechanistically diverse involvement of the melastatin subfamily channels in the prostate cancer development, TRPM2 is one more known member that controls proliferation of prostate cancer cells by inhibiting the nuclear ADP-ribosylation." (PMID 29671777, 2018). "Similarly, RNAi silencing of TRPM2 in prostate cancer cells decrease their proliferation, which suggests that TRPM2 has a role in facilitating prostate cancer cell propagation and growth." (PMID 25760245, 2015). "This previous study demonstrated a nuclear localization of TRPM2 in prostate cancer cells." (PMID 25760245, 2015). "Furthermore, expression of TRPM2 has been demonstrated in several tumors such as hepatocellular carcinoma, prostate cancer, lymphoma, leukemia, and lung cancer cell lines in which TRPM2 reportedly may foster cell death." (PMID 32423430, 2020). "Moreover, expression of TRPM2 has been demonstrated in several tumor entities such as insulinoma, hepatocellular carcinoma, prostate cancer, lymphoma, leukemia, and lung cancer cell lines in which TRPM2 reportedly may foster cell death." (PMID 26839633, 2016). "Through the regulation of TRP channels like TRPM2 and TRPM7 in neuronal cells and prostate cancer cells, the RESV therapy altered Ca2+ influx." (PMID 38976129, 2024). "After depletion of TRPM2 with siRNA, the progress of prostate cancer, without non-cancerous cells, was lowered." (PMID 37337283, 2023). "The siRNA sequence we utilized was previously shown to effectively knock down TRPM2 expression in both noncancerous prostate cells and prostate cancer cells." (PMID 25760245, 2015). "It was reported that selectively knocking down TRPM2 inhibited the growth of prostate cancer cells but not of non-cancerous cells." (PMID 26100964, 2015). "However, a major quantity of TRPM2 was located in the nucleus and the non-nuclear fraction of prostate cancer cells." (PMID 37337283, 2023). "Moreover, the selectively knocked down TRPM2 inhibited the growth of prostate cancer cells but not of non-cancerous cells." (PMID 28008929, 2016).
Alzheimer disease (20 papers, 2011 to 2025). A progressive, neurodegenerative disease characterized by loss of function and death of nerve cells in several areas of the brain leading to loss of cognitive function such as memory and language. "TRPM2 has also been associated with Alzheimer’s disease (AD), a common neurodegenerative disorder primarily associated with the accumulation of β-amyloid (Aβ) plaques, Ca2+ overload, and increased ROS." (PMID 37576339, 2023). "It is also worth mentioning that TRPM2 has been implicated in Alzheimer’s disease." (PMID 33924946, 2021). "Interestingly, both GSK-3β and TRPM2 channels have been implicated in a number of overlapping pathophysiological processes ranging from pancreatic insulin secretion to Alzheimer's disease." (PMID 22188973, 2011). "Moreover, TRPM2 is implicated in innate immunity and the pathobiology of Alzheimer disease." (PMID 27618067, 2016). "Glutathione depletion linked to oxidative stress induces apoptosis mediated through TRPM2 channels in microglial cells with Alzheimer’s disease model." (PMID 39329114, 2024). "Park and colleagues suggested the role of PARPs in TRPM2 activation during high oxidative stress and investigated this mechanism in the context of Alzheimer disease." (PMID 38390373, 2023). "TRPM2 has been identified as a promising drug target in diseases of the central nervous system, such as neuropathic pain, bipolar disorder and Alzheimer’s disease, and more potential inhibitors are expected to be identified." (PMID 32503336, 2020). "Emerging evidence supports an important role for the ROS-sensitive TRPM2 channel in mediating age-related cognitive impairment in Alzheimer’s disease (AD), particularly neurotoxicity resulting from generation of excessive neurotoxic Aβ peptides." (PMID 29416015, 2018). "Under pathological conditions, such as post-ischemic reperfusion injury and potentially in Alzheimer's disease, TRPM2 activity leads to Ca2+ dysregulation and cell death." (PMID 27383051, 2016). "Additional mechanisms such as ROS-ADPR- Poly adenosine diphosphate ribose polymerase mediated TRPM2 current in microglia thereby increase intracellular Ca2+ and thereby induce apoptosis of hippocampal pyramidal neurons in Alzheimer’s disease (Övey and Naziroğlu, 2015)." (PMID 39329114, 2024). "Similarly, endothelial dysfunction mediated by ROS-activated TRPM2 was also found to accelerate the development of Alzheimer’s disease and aggregate inflammatory lung injury." (PMID 35159300, 2022). "Therefore, it would be of great interest to test the influence of TRPM2 regulation via phosphoinositides in Alzheimer’s disease." (PMID 33924946, 2021). "Therefore, ROS-induced TRPM2 channel activation has been proposed to contribute to the pathogenesis of ischemia stroke and neurodegenerative conditions such as Alzheimer’s disease (AD) and Parkinson’s diseases (PD)." (PMID 30625984, 2019). "Finally, the TRPM2 channel is involved in cell damage following heart attacks or stroke and may contribute to Alzheimer’s disease, Parkinson’s disease and bipolar disorder as well." (PMID 27383051, 2016).
Cerebral ischemia (20 papers, 2013 to 2025). Restriction of arterial blood supply to the brain associated with insufficient oxygenation to support the metabolic requirements of the tissue. "Being the first messenger for TRPM2 channels, bilirubin triggers and exacerbates neurotoxicity associated with brain ischemia by directly driving Ca2+ influx through these channels to elevate neuronal excitability and activate Ca2+-dependent cell-death pathways." (PMID 36921602, 2023). "We have extensive evidence for a sexually dimorphic response of TRPM2-induced acute injury following global and focal cerebral ischemia." (PMID 40352737, 2025). "Recently, numerous antioxidants, like edaravone and N‐acetylcysteine (NAC), were found to protect nerve cells against cerebral ischemia injury by blocking TRPM2‐mediated Ca2+ influx and increasing neuronal survival." (PMID 36527242, 2023). "In microglia, upregulation of TRPM2 channels continually occurs weeks after focal cerebral ischemia." (PMID 36527242, 2023). "Cerebral ischemia-induced TRPM2 activation triggers abnormal intracellular Ca2+ accumulation and cell death, which in turn causes irreversible brain damage." (PMID 33455532, 2021). "In adults, much work has been done to implicate androgens in the activation of TRPM2, contributing to sex-specific neuronal injury after brain ischemia." (PMID 34659399, 2021). "Dexmedetomidine suppressed cerebral-ischemia-induced oxidative stress and apoptosis by inhibiting the activation of the TRPM2 and TRPV1 channels in neurons." (PMID 31682592, 2019). "The inhibitory effect of DEX in cerebral ischemia-induced TRPM2 and TRPV1 activation should be considered a potential pharmacological target for itching caused by cerebral ischemia-mediated activation of pain and brain injuries." (PMID 27872485, 2016). "In conclusion, results suggest that DEX treatment reduces cerebral ischemia-induced oxidative stress, cell death, and intracellular Ca2+ signaling through inhibition of TRPM2 and TRPV1 in the rat hippocampus and DRG." (PMID 27872485, 2016). "He focused on transient receptor potential melastatin (TRPM) 4 cation channels in neurodegeneration during EAE and TRPM2 in the MCAO model of cerebral ischemia." (PMID 24330587, 2013). "However, this is the first study to assess the role of TRPM2 channels in juvenile cerebral ischemia, showing a complex pattern of involvement in prolonged dysfunction, but not acute cell death." (PMID 34659399, 2021). "A growing number of studies have consistently revealed that TRPM2 is detrimental in brain ischemia." (PMID 33455532, 2021). "In addition, numerous studies have revealed that TRPM2 is detrimental to brain ischemia." (PMID 35055089, 2022). "Further, using an in vitro model of brain ischemia, we demonstrated CD38 inhibition reduces clustering of GABAergic synaptic components via a TRPM2-dependent pathway." (PMID 40822706, 2024). "Overall, our data identify FPP as a newly identified danger signal to trigger acute cell death and suggest that the FPP/TRPM2 signaling axis and the MVA pathway exhibit important roles in brain ischemia and potentially neurodegenerative diseases." (PMID 33901180, 2021). "On this basis, DEX’s inhibition of the TRPM2 and TRPV1 currents contributes to the prevention or limitation of brain injuries during cerebral ischemia." (PMID 27872485, 2016). "Furthermore, DEX efficiently has been reported to reduce cumene hydroperoxide/ADP-ribose-triggered TRPM2 and TRPV1 densities in the neurons of mice with cerebral ischemia." (PMID 37269788, 2023). "Further evidence demonstrated that male cell death after cerebral ischemia was mediated predominantly by excessive ROS production and subsequent overactivation of PARP-1 and TRPM2, eventually resulting in mitochondrial dysfunction, the release of apoptosis-inducing factor, and cell death." (PMID 33455532, 2021).
Cerebral ischemia (continued). "To address this interaction between DEX, TRPM2 and TRPV1, we investigated the protective actions of DEX treatment on apoptosis, oxidative stress levels, Ca2+ entry values as well as involvement of TRPM2 and TRPV1 activations on the values in the DRG and HIPPO neurons in rat with cerebral ischemia." (PMID 27872485, 2016). "Dexmedetomidine (DEX) may act as an antioxidant through regulation of TRPM2 and TRPV1 channel activations in the neurons by reducing cerebral ischemia-induced oxidative stress and apoptosis." (PMID 27872485, 2016). "The aim of the study was to evaluate whether DEX functionally interacts with TRPM2 and TRPV1 in the HIPPO and DRG neurons of rats with cerebral ischemia." (PMID 27872485, 2016). "Therefore, DEX may reduce the entry of overload Ca2+ via modulation of TRPM2 and TRPV1 channel activations in the HIPPO and DRG neurons of rats with cerebral ischemia, and this effect should be clarified." (PMID 27872485, 2016). "Therefore, we suggest that DEX involved changes of Ca2+ entry through activations of TRPM2 and TRPV1 channels and the activations resulted in production of mitochondrial membrane depolarization-induced free oxygen radical in cerebral ischemia-induced brain HIPPO neuronal injury and pain induction." (PMID 27872485, 2016). "In addition, non-specific inhibitors of TRPM-2 channels, such as 2-APB, neuroprotect male but not female animals after brain ischemia-reperfusion." (PMID 35806455, 2022). "However, there have been no reports on overload Ca2+ entry via activations of TRPM2 and TRPV1 in rats with cerebral ischemia." (PMID 27872485, 2016).
colitis (20 papers, 2012 to 2025). Inflammation of the colon. "Several studies have shown that the formation of immune infiltrates and colonic ulceration is reduced in TRPM2-deficient mice in a DSS-induced colitis model." (PMID 38731999, 2024). "Consistent with this notion, the milder course of DSS colitis of Trpm2-/- mice is associated with reduced neutrophil but similar T cell accumulation." (PMID 35095852, 2021). "In a colitis model, TRPM2 has been implicated in inflammatory pathways, specifically as a key participant in chemokine production." (PMID 32823895, 2020). "Last, DSS-treated Trpm2 KO mice did not exhibit weight loss and/or ulceration of the colon, suggesting that Trpm2 KO mice were largely protected from DSS-mediated colitis." (PMID 27618067, 2016). "TRPM2-deficient mice are more resistant to chronic experimental colitis due to defective chemokine (C-X-C motif) ligand 2 (CXCL2) production by monocytes and reduced neutrophil infiltration." (PMID 23631390, 2013). "For instance, TRPM2 expression correlates with monocyte-derived CXCL2 secretion and neutrophil infiltration in colitis, while TRPM2-deficient mice show reduced IL-12, interferon levels, and nitric oxide synthase expression in splenic macrophages during Listeria infection." (PMID 41293090, 2025). "For example, TRPM2 deficiency suppressed exacerbation of inflammation in mouse model of colitis." (PMID 32513195, 2020). "The researchers induced colitis-associated colon cancer in mice and showed that the expression levels of the three TRP channels (TRPA1, TRPM2, TRPV1) were overexpressed." (PMID 40813985, 2025). "Immune cell infiltration and intestinal inflammation severity have been improved in TRPM2-knockout mice with DSS-induced colitis (Ref." (PMID 38659380, 2024). "Three channels TRPA1, TRPM2 and TRPV1 have been shown to influence apoptosis in mice with colitis-associated colon cancer (azoxymethane (AOM)/DSS model)." (PMID 38731999, 2024). "In a rat model of ulcerative colitis, the increased expression of TRPM2 was detected in the colon, and TRPM2 inactivation reduced inflammation in a mouse model of DSS-induced colitis." (PMID 39596193, 2024). "This evidence reminds us that TRPM2 can exert pro-inflammatory effects in the colitis via its essential role in macrophages and NF-κB signaling pathway." (PMID 32153564, 2020). "The similar phenotype of CD38-/- and TRPM2-/- mice in the DSS colitis model further suggests that ADPR generation is central to this function of CD38." (PMID 25938500, 2015). "The production of IL-12 and IFN-γ after DSS-induced colon inflammation was significantly decreased in the TRPM2-KO mice." (PMID 26300888, 2015). "It has been shown that TRPM2 channels control neutrophil infiltration in a mouse model of colitis by regulating CXCL2 chemokine production in monocytes." (PMID 23631390, 2013). "Additionally, in colitis-associated colon cancer, stimulation of TRPA1, TRPM2, and TRPV1 increases mitochondrial ROS and Zn2+ dysregulation, promoting apoptotic cell death, an effect mitigated by antioxidant treatment with Sambucus ebulus L." (PMID 40813985, 2025). "A rat model of TNBS-induced colitis showed increased expression of TRPM2 in the distal colon." (PMID 38731999, 2024). "TRPM2 may play a pro-inflammatory role in colitis through its essential roles in macrophages and nuclear factor kappa-B (NF-κB) signalling." (PMID 38659380, 2024). "The TRPM2-KO mice manifested significantly reduced severity of colitis." (PMID 26300888, 2015). "However, according to existing data on other TRP channels and the observed effects in animal colitis models, there is a need to study positive/negative events associated with TRPM2, TRPM3, TRPM8, and TRPV2 channels in humans." (PMID 38731999, 2024). "Therefore, TRPM2 may be involved in the progression of colitis through its implication in oxidative stress signaling or other immunomodulatory effects." (PMID 38731999, 2024).
colitis (continued). "Interestingly, TRPM2-/- mice also display only mild inflammation in the DSS colitis model." (PMID 25938500, 2015). "The search terms used were "Transient Receptor Potential Channels", "TRP channels", "TRPV1", "TRPA1", "TRPV4", "TRPV2", "TRPM2", "TRPM3", "TRPM7", "TRPM8", "TRPC3", "colitis", "inflammatory bowel disease", "IBD", "ulcerative colitis", "Crohn Disease"." (PMID 41096659, 2025). "In the TRPM2 -/- mouse model of DSS, the expression of CXCL2 was strongly inhibited, suggesting that TRPM2 -/- mice largely mediate protection from DSS colitis." (PMID 37404813, 2023). "For TRPM2, its expression was enhanced in the distal colon of a TNBS-colitis rat model and administration of TRPM2 antagonist or TRPM2 deficiency-attenuated visceromotor response to colorectal distension." (PMID 35677724, 2022). "Further studies are required, including other TRP channels (e.g., TRPM2, TRPM3, TRPM8, TRPV2), which have demonstrated beneficial or negative effects on intestinal inflammation in animal models of colitis, to confirm/refute the severity of these effects in humans." (PMID 38731999, 2024). "In TNBS-induced rat colitis, the VMR was enhanced and could be ameliorated by an oral administration of TRPM2 antagonist (econazole)." (PMID 32153564, 2020). "In the colitis model, the TRPM2 channel controls CXCL2 production in monocytes and consequently affects neutrophil infiltration, and in the lung inflammation model, TRPM2 plays a protective role by preventing ROS production in neutrophils." (PMID 23631390, 2013). "Therefore, TRPM2-mediated Ca2+ influx is important in ROS-induced CXCL2/CXCL8 production by monocytes and neutrophil infiltration that, if heightened to colon inflammation, lead to colitis." (PMID 26300888, 2015). "In response to dextran sulfate sodium (DSS)-induced colon inflammation, a model of ulcerative colitis, there was strong increase in the CXCL2 expression in monocytes from the WT but not TRPM2-KO mice." (PMID 26300888, 2015).